TYK2 (tyrosine kinase 2)
Diseases named in the same sentence as TYK2 in open-access papers (continued):
Sharing a sentence is not in itself a finding about the gene and the disease.
Autosomal recessive hyper-IgE syndrome (3 papers, 2011 to 2014). Autosomal recessive hyper IgE syndrome (AR-HIES) is a very rare severe primary immunodeficiency disorder characterized by the clinical triad of highly elevated serum IgE levels, recurring staphylococcal skin abscesses, and recurrent pneumonia. "A mutation in the dedicator of the cytokinesis 8 gene has been identified as the cause of many cases with autosomal recessive hyper-IgE syndrome and, in one patient, a mutation in tyrosine kinase 2 gene has been demonstrated." (PMID 22085750, 2011). "Initially, in a single patient with autosomal recessive HIES, a null mutation in the tyrosine kinase 2 (TYK2) gene was identified." (PMID 22085750, 2011). "Autosomal recessive hyper IgE syndrome is associated with a deficiency of tyrosine kinase 2 (TYK2)." (PMID 25379309, 2014).
celiac disease (3 papers, 2013 to 2025). An autoimmune genetic disorder with an unknown pattern of inheritance that primarily affects the digestive tract. "We suspected different diagnoses such as Noonan syndrome, celiac disease, polyendocrine diseases for short stature, food allergies, hypereosinophilic syndromes, IPEX, autosomal-dominant hyperimmunoglobulin E syndrome and hyperimmunoglobulin E associated with Tyk2 deficiency." (PMID 24199610, 2013).
cervical carcinoma (3 papers, 2020 to 2023). A carcinoma arising from either the exocervical squamous epithelium or the endocervical glandular epithelium. "A refined risk score model, comprising PLA2G7, TNF, TYK2, F2, and NRP1, effectively stratified cervical cancer patients into distinct risk groups." (PMID 37704909, 2023). "Claudin-9 expression is related to the increased metastatic ability of the hepatocytes by disturbing the TyK2/Stat3 signaling pathway, and it has been related to lymphatic metastasis in cervical carcinoma." (PMID 39296813, 2021).
depression (3 papers, 2023 to 2025). "Currently, only the analgesic drug meptazinol has been discovered to upregulate AHI1 and Tyk2 expression in a mouse model of depression, suppressing viral infection." (PMID 38916735, 2024). "Depression-related arginine vasopressin (AVP) reduces AHI1 expression, which disrupts Tyk2 and interferon signaling, further compromising immune defense." (PMID 40242760, 2025). "Therefore, the reduction of AHI1 ultimately results in the downregulation of Tyk2 and subsequent attenuation of IFN-I signaling activity in macrophages obtained from depression." (PMID 38916735, 2024).
eczema (3 papers, 2020 to 2024). "This panel should include the ten HIES genes, DOCK8 gene, TYK2 gene, genes that could be responsible for atypical clinical presentations, and genes associated with moderate to severe refractory eczema and elevated Immunoglobulin E." (PMID 36703986, 2022). "Other recessive mutations, such as those in the TYK2 and PGM3 genes, have been associated with hyper-IgE syndrome, as have other genetic anomalies leading to hyper IgE, eczema, and dysimmune manifestations." (PMID 38983983, 2024).
herpes zoster (3 papers, 2023 to 2025). A common dermal and neurologic disorder caused by reactivation of the varicella-zoster virus that has remained dormant within dorsal root ganglia, often for decades, after the patient's initial exposure to the virus in the form of varicella (chickenpox). "Indeed, there were no alarming reports of herpes zoster, opportunistic infections, thromboembolic events in TYK2 inhibitors clinical trials, in contrast to those on JAK 1, 2, and 3 inhibitors, both in PsO and in other diseases." (PMID 38892802, 2024).
Hyperglycemia (3 papers, 2015 to 2025). An increased concentration of glucose in the blood. "We found that TYK2 inhibition prevents the onset of hyperglycemia in both RIP-LCMV-GP and NOD mice." (PMID 38766166, 2024). "While Tyk2 KO mice developed hyperglycaemia, MIP-Tyk2 Tg Tyk2 KO mice could maintain normal blood glucose levels." (PMID 25849081, 2015).
malignant peripheral nerve sheath tumor (3 papers, 2019 to 2021). Malignant peripheral nerve sheath tumor (MPNST) is a rare and often aggressive soft tissue sarcoma occurring in a wide range of anatomical sites. "Our laboratory utilized NGS and identified activating TYK2 mutations in malignant peripheral nerve sheath tumors (MPNST), an aggressive subtype of sarcomas associated with the Neurofibromatosis type 1 (NF1) cancer predisposition syndrome." (PMID 34439323, 2021). "In Malignant peripheral nerve sheath tumors (MPNST), TYK2 induces cell proliferation and promotes MPNST progression through inhibiting cell death." (PMID 33731185, 2021).
rheumatic diseases (3 papers, 2023 to 2024). "JAKi, with varying selectivity for JAK1, JAK2, JAK3, and Tyk2, have then the role of disrupting proinflammatory cytokine cascades in rheumatic diseases." (PMID 38554250, 2024). "In treating rheumatic diseases, 4 members of the Janus kinases family (JAK1, JAK2, JAK3, and tyrosine kinase-2; TYK2) and their 7 downstream signal transducers and activators of transcription (STATs) are currently of greatest interest." (PMID 37171669, 2023).
sarcoidosis (3 papers, 2022 to 2026). Sarcoidosis is a multisystemic disorder of unknown cause characterized by the formation of immune granulomas in involved organs. "An MR study showed that genetically proxied TYK2 inhibition was associated with reduced sarcoidosis susceptibility." (PMID 40075078, 2025). "Given the central role of these pathways in granuloma formation, inhibiting TYK2 may provide a more targeted approach to modulating immune responses in sarcoidosis compared to the inhibition of JAK inhibitors." (PMID 41446689, 2026). "Thus, clinical trials to evaluate the safety and efficacy of TYK2 inhibitors in treating sarcoidosis are urgently needed for therapeutic development." (PMID 40075078, 2025). "TYK2 inhibition may represent a promising new therapeutic avenue for sarcoidosis." (PMID 41446689, 2026). "We also found that the activity of other cytokines including GM-CSF (JAK2), IL-15 (JAK1/3), IL-6 (JAK1/2), IL-12 (JAK2/TYK2) and TNF (JAK-independent) are also evident in sarcoidosis." (PMID 35668129, 2022).
Sepsis (3 papers, 2022 to 2024). Sepsis is defined as life-threatening organ dysfunction caused by a dysregulated host response to infection. "Of note, LPS scarcely induced Stat1 and Tlr7 expression in Tyk2−/−cells, supporting the idea of a downregulated inflammation leading to the lack of sepsis described in Tyk2−/− mice in response to LPS." (PMID 38683377, 2024).
Stroke (3 papers, 2023). Sudden impairment of blood flow to a part of the brain due to occlusion or rupture of an artery to the brain. "Multiple variants in the SLCO1B1, PRIM1, APOB, TYK2, TSEN15, CYP4F2, and MST1 genes were previously suggested as risk factors for stroke with p-values < 1.0 × 10−5 in a GWAS on German pediatrics." (PMID 37895268, 2023).
type 2 diabetes (3 papers, 2015 to 2023). "The TYK2 gene has a critical importance in the etiology of autoimmune and inflammatory diseases, specifically type 1 and type 2 diabetes, due to its association with the pancreatic β-cell-specific suppression of cytokine response including IFN." (PMID 36979105, 2023). "Polymorphisms of TYK2 gene at the promoter region and exons were studied among 331 healthy controls, and 302 patients with T1D and 314 with type 2 diabetes (T2D) in the Japanese." (PMID 26288847, 2015). "This study investigated the relationship between a TYK2 promoter variant (TYK2PV) and insulin secretion in type 2 diabetes patients." (PMID 33799705, 2021).
vitiligo (3 papers, 2021 to 2023). Generalized well circumscribed patches of leukoderma that are generally distributed over symmetric body locations and is due to autoimmune destruction of melanocytes. "It, along with Brepocitinib, a TYK2/JAK1 inhibitor, are currently being evaluated for their efficacy and safety profile in active vitiligo in combination with phototherapy." (PMID 36902341, 2023). "TYK2, another member of the JAK family, plays a ubiquitous role in signal transduction with type I interferon (IFN-α), which also induces the expression of CXCL9 and CXCL10 by keratinocytes in vitiligo." (PMID 34868078, 2021). "Interestingly, a phase 2 clinical trial evaluating the efficacy of systemic administration of a JAK1/TYK2 inhibitor is ongoing (NCT03715829) and will provide new insights into the physiopathology of vitiligo." (PMID 33936032, 2021).
asthma (2 papers, 2021 to 2022). "Neutrophils from healthy subjects, severe asthma and COPD patients showed a higher expression of JAK2 followed by JAK3 and in a lesser extent of JAK1, while levels of TYK2 were the lowest." (PMID 35332239, 2022).
brucellosis (2 papers, 2017 to 2022). Brucellosis is a bacterial infection that spreads from animals to people via unpasteurized dairy products or by exposure to contaminated animal products or infected animals. "We found that 48% of the 25 patients with AR complete TYK2 deficiency had mycobacterial diseases (due to BCG, EM, or M.tb) and 16% had salmonellosis, brucellosis, or leishmaniasis, as often reported in patients with MSMD." (PMID 36094518, 2022). "A second patient, also with small deletions in TYK2 and the absence of protein on western blots like the first patient, presented with BCG disease and brucellosis, but had normal IgE levels and no skin lesions." (PMID 29230214, 2017).
candidiasis (2 papers, 2020 to 2021). Infection with the organism Candida. "Deficiency of tyrosine kinase 2 (Tyk2) that participates in signal transduction for various cytokine receptors leads to impaired helper T cell type 1 (Th1) differentiation and accelerated helper T cell type 2 (Th2) differentiation in candidiasis." (PMID 34490039, 2021).
cicatricial alopecia (2 papers, 2025). Scarring hair loss, also known as cicatricial alopecia, is the loss of hair which is accompanied with scarring. "A phase 2a study evaluating the efficacy of oral dual JAK1/tyrosine kinase 2 inhibitor brepocitinib in cicatricial alopecias found significant downregulation of inflammatory biomarkers, including CCL5, and demonstrated a favorable safety profile." (PMID 40778340, 2025).
cutaneous T-cell lymphoma (2 papers, 2019 to 2022). "Furthermore, we measured TYK2 expression in 6 ALCL cell lines (ALK+: K299, SR786, SUDHL-1, SUP-M2; and ALK−: Mac1, Mac2a), the cutaneous T-cell lymphoma cell line MyLa bearing the NPM1-TYK2 fusion and PBMCs." (PMID 30131584, 2019).
eosinophilia (2 papers, 2012 to 2025). "We then performed panel sequencing for eosinophilia, which revealed a biallelic variant of TYK2 (encoding tyrosine kinase 2) that was also identified by whole-exome sequencing (WES), (c.3388C>T, p.Arg1130*)." (PMID 40949057, 2025).
esophageal squamous cell carcinoma (2 papers, 2021 to 2022). Esophageal squamous cell carcinoma (ESCC) is a type of esophageal carcinoma (EC) that can affect any part of the esophagus, but is usually located in the upper or middle third. "Cirsiliol was able to directly bind the tyrosine kinase 2 (TYK2), targeting its signaling through STAT3, thus suppressing esophageal squamous cell carcinoma growth." (PMID 36231131, 2022).
head and neck squamous cell carcinoma (2 papers, 2022 to 2023). A squamous cell carcinoma that arises from any of the following anatomic sites: lip and oral cavity, nasal cavity, paranasal sinuses, pharynx, larynx, and salivary glands. "Nevertheless, the roles of TYK2 in the prognosis and immune infiltration of head and neck squamous cell carcinoma (HNSCC) remain to be elucidated." (PMID 36531252, 2022).
Hodgkins lymphoma (2 papers, 2019 to 2020). A heterogeneous group of malignant lymphoid neoplasms of B-cell origin characterized histologically by the presence of Hodgkin and Reed-Sternberg (HRS) cells in the vast majority of cases. "In Hodgkin lymphoma cells, inhibition of HSP90 led to loss of JAK1, JAK3, and Tyk2, and constitutive pY of STAT1, 3, 5, and 6 was ablated." (PMID 32272626, 2020).
Infertility (2 papers, 2017). "Recently, it has been suggested that CYP17, VDR, MUC17, COX-2, WNT4, E-cadherin, CYP19, CYP17, TYK2, NFKB1, and MUC2 gene variants also contributed to endometriosis-related infertility." (PMID 28405865, 2017).
latent infection (2 papers, 2016 to 2023). "To further determine the involvement of YTHDF2 in degradation of TYK2 mRNA, we monitored the protein levels of TYK2 after silencing YTHDF2 in both latent infection and after reactivation." (PMID 36918845, 2023).
leprosy (2 papers, 2020 to 2023). Leprosy is a chronic infectious disease affecting primarily the skin and peripheral nervous system. "However, we cannot rule out the possibility of other rare or common variants of IL23R or TYK2 being related to leprosy susceptibility in the Amazon population." (PMID 32433683, 2020). "Here, we investigated whether SNPs located in eleven genes: CCDC122/LACC1, IFNG, IL6, IL10, IL23R, LRRK2, NOD2, PACRG/PRKN, TLR1, TNF and TYK2 are associated to leprosy susceptibility in a population in the North of Brazil." (PMID 32433683, 2020). "Thus, the leprosy susceptibility loci, including NOD2, RIPK2, TNFSF15, LACC1, LRRK2, IL12B, and HLA‐DR in phagocytes and IL23R, TYK2, and CSK in T cells, may interfere with the synergistic antimicrobial response between phagocytes and T cells." (PMID 38020709, 2023).
lymphoproliferative disorders (2 papers, 2021 to 2022). "Translocations of TYK2 have been found in lymphoproliferative disorders." (PMID 33672930, 2021).
pancreatic cancer (2 papers, 2022 to 2024). "The result of human protein atlas (HPA) database showed the expression of TRAF1 and TYK2 were low in pancreatic cancer, the expression of MET was high." (PMID 38363947, 2024).
respiratory failure (2 papers, 2021 to 2025). The significant impairment of gas exchange within the lungs resulting in hypoxia, hypercarbia, or both, to the extent that organ tissue perfusion is severely compromised. "We report the case of a patient with complete TYK2 deficiency and virally induced hypereosinophilia and respiratory failure who responded to IL-5 blockade." (PMID 40949057, 2025). "Thus, we report the case of a patient with complete TYK2 deficiency and virally induced hypereosinophilia and respiratory failure who responded to IL-5 blockade." (PMID 40949057, 2025).
respiratory infection (2 papers, 2020 to 2022). "In the current work, a recessive TYK2 deficiency is reported in a patient suffering from BCG disease and recurrent respiratory infection." (PMID 32537443, 2020). "P8 (c.2466+1G>T/c.2466+1G>T), with a previously unknown essential splice-site mutation in TYK2, had respiratory infections for which the causal microbe was not identified, and no signs of HIES." (PMID 36094518, 2022).
sarcoma (2 papers, 2019 to 2021). A usually aggressive malignant neoplasm of the soft tissue or bone. "We first set out to examine TYK2 expression in a set of MPNSTs and other sarcomas in order to determine if TYK2 expression could serve as a diagnostic biomarker for MPNSTs." (PMID 31278855, 2019). "Genomic and proteomic screens by our lab and others have revealed tyrosine kinase 2 (TYK2) as an oncogene promoting progression and metastases of many types of carcinomas, sarcomas, and hematologic cancers." (PMID 34439323, 2021). "Given that TYK2 is expressed at high levels in the majority of MPNSTs, we went on to look at the functional role in this subset of sarcomas." (PMID 31278855, 2019). "Immunohistochemistry was utilized to examine expression of TYK2 in MPNSTs and other sarcomas." (PMID 31278855, 2019). "While, we had initially hoped that expression of TYK2 could serve as a potential biomarker distinguishing MPNSTs from other soft tissue sarcomas, we observed high expression in 38%‐89% of other sarcomas as well." (PMID 31278855, 2019). "Nonetheless, these data do suggest that TYK2 protein overexpression is prevalent in malignant tumors and could be targetable in MPNSTs as well as other sarcomas." (PMID 31278855, 2019). "As such, TYK2 expression is unlikely to serve as a diagnostic biomarker for MPNSTs, but these data do suggest that TYK2 could be a therapeutic target in other sarcoma subtypes as well." (PMID 31278855, 2019).
skin infection (2 papers, 2020 to 2024). An inflammatory process affecting the skin, caused by bacteria, viruses, parasites, or fungi. "In this study, we report that TYK2-mediated immune signaling increases the sensitivity to C. albicans skin infections, which is in sharp contrast to the protective role of TYK2 in the host defense against bacterial and viral infections." (PMID 39622833, 2024). "Further studies are needed to investigate the potential beneficial effects of TYK2 inhibitors on the immune defense against C. albicans skin infections." (PMID 39622833, 2024). "In this study, we show that mice lacking TYK2 or its enzymatic activity exhibit enhanced resistance to C. albicans skin infections, limiting fungal spread and accelerating wound healing." (PMID 39622833, 2024).
soft tissue sarcoma (2 papers, 2019 to 2021). A malignant neoplasm arising from muscle tissue, adipose tissue, blood vessels, fibrous tissue, or other supportive tissues excluding the bones. "Genomic, transcriptomic and proteomic assays have led to identification of tyrosine kinase 2 (TYK2) mutations, fusion proteins and expression changes in a variety of hematological cancers, carcinomas and soft-tissue sarcomas." (PMID 34439323, 2021). "Genomic screens have also implicated TYK2 as a pro-survival gene in soft-tissue sarcomas." (PMID 34439323, 2021).
Stomach Adenocarcinoma (2 papers, 2020 to 2021). "Using an RNA-seq bioinformatics approach to compare stomach adenocarcinoma and normal tissues, TYK2 and JAK3 mRNA expression were positively associated with tumor grade, stage, and lymph node metastasis status, and patients with high TYK2 expression in their tumors had shorter overall survival." (PMID 34439323, 2021). "In addition, RNA sequencing (RNA-seq) of the transcriptome revealed that TYK2 and JAK3 mRNA levels were significantly increased in stomach adenocarcinoma, and both proteins were found to be prognostic biomarkers." (PMID 34439323, 2021).
upper respiratory tract infection (2 papers, 2023 to 2025). "The most common complaints among individuals with TYK2 inhibitors treatment are headache, upper respiratory tract infection, nausea, diarrhoea, and increased circulating levels of creatinine and liver enzymes." (PMID 36842216, 2023).
uveitis (2 papers, 2023 to 2026). An inflammatory process affecting a part of or the entire uvea. "Future development of non-selective Tyk2 inhibitors will be focused on diseases where therapeutic benefit outweighs potential safety concerns, as illustrated by the current indications pursued for brepocitinib (SLE, dermatomyositis, and uveitis)." (PMID 36834806, 2023).
AIDS (1 paper, 2020). A syndrome resulting from the acquired deficiency of cellular immunity caused by the human immunodeficiency virus (HIV). "Seven TYK2 variants have been associated with AIDs in Europeans, and establishing their causality remains challenging." (PMID 31961910, 2020). "Seven TYK2 variants have been associated with AIDs in European cohorts and for most the minor allele is protective." (PMID 31961910, 2020).
anemia (1 paper, 2015). A reduction in the number of red blood cells, the amount of hemoglobin, and/or the volume of packed red blood cells. "Compared to ruxolitinib, JTE-052 might be expected to have a lower risk of anemia in the clinical setting owing to its relatively weak inhibition of JAK2/Tyk2 signaling pathway." (PMID 25387665, 2015).
B-cell acute lymphoblastic leukemia (1 paper, 2024). A neoplasm of lymphoblasts committed to the B-cell lineage, typically composed of small to medium-sized blast cells. "Previously, our group reported in patients with B cell acute lymphoblastic leukemia TYK2 variants that impaired the response to IFNα in vitro." (PMID 38683377, 2024).